ELN (elastin)
Diseases named in the same sentence as ELN in open-access papers (continued):
Sharing a sentence is not in itself a finding about the gene and the disease.
genetic disorder (17 papers, 2016 to 2025). "It is a genetic disorder that is caused by a sporadic microdeletion of chromosome 7, which includes the elastin gene." (PMID 39099908, 2024). "Mutations in genes for proteins involved with microfibrillar or elastin network integrity and organization cause similar hereditary diseases to elastinopathies and fibrillinopathies." (PMID 37001705, 2023). "Disruptions of ADAM metallopeptidase with thrombospondin (ADAMTS) and ADAMTS-like (ADAMTSL) proteins also cause elastin-related hereditary disease due to their interactions with fibrillin-1 and LTBPs, however, their role is not clear." (PMID 37001705, 2023). "Even apart from genetic disorders of collagen and elastin, a familial predisposition has been shown as well." (PMID 27527829, 2016). "However, injury, genetic disorders, and aging can lead to elastin damage and irreversible loss of skin integrity and elasticity due to the lack of elastin turnover and physiological repair mechanisms." (PMID 37650117, 2023). "Elastic fiber is also a significant component of the heart tissue and cardiac structural abnormalities are observed in various elastin related hereditary diseases." (PMID 37001705, 2023). "As observed in elastin-related hereditary diseases, the effect on joint biomechanics can be highly variable, with both excessive stiffness and flexibility observed." (PMID 37001705, 2023). "PXE is a genetic disease characterized by a metabolic abnormality of elastin in elastic fibers, thus affecting organs with abundant elastic fibers such as the skin, eyes, and cardiovascular system." (PMID 28978321, 2017).
connective tissue disorder (15 papers, 2012 to 2025). A disease involving the connective tissue. "The patient’s skin biopsy indicated an absence in the coordination of elastic fiber formation and the integration of elastin fibers with collagen fibers, suggesting an underlying connective tissue disorder." (PMID 30111362, 2018). "Examination of the patient’s skin biopsy revealed abnormalities in elastin and collagen fibrils that suggest an underlying connective tissue disorder." (PMID 30111362, 2018). "Since then, several researchers have described the consequences of the ingestion of certain plants on connective tissue disorders, especially on collagen and elastin cross-linking." (PMID 33669630, 2021). "EDS and OI are connective tissue disorders involving the collagen–elastin matrix that have overlapping clinical features, including bone fragility." (PMID 34204301, 2021). "Reduced ELN expression may lead to premature tissue aging and structural deterioration, affecting tissue functionality and contributing to various connective tissue disorders." (PMID 40958908, 2025). "ARCL2A is a clinically highly variable group of connective tissue disorders characterized by inelastic skin due to lack of mature elastin fibers in the extracellular matrix." (PMID 30474613, 2019).
metabolic disease (6 papers, 2014 to 2023). A congenital disorder (due to inherited enzyme abnormality) or acquired (due to failure of a metabolically important organ) disorder resulting from an abnormal metabolic process. "In this manuscript, the elastin network is shown to be present in murine adipose tissue, and our results implicate elastin insufficiency as a susceptibility factor to metabolic disease in mice." (PMID 26167199, 2014). "Cardiovascular and metabolic disease is closely associated with degradation of elastin." (PMID 37001705, 2023). "As discussed in the following section covering elastin degradation in cardiovascular and metabolic diseases, protease activity which degrades elastic fibers can be a critical step preceding the process of vascular calcification." (PMID 37001705, 2023). "Further, Eln+/−; ApoE−/− mutants have significant impairment of insulin sensitivity by insulin tolerance testing, independent of body weight or diet, suggesting that elastin insufficiency predisposes to metabolic disease in susceptible individuals." (PMID 26167199, 2014). "But beyond this fundamental role, a huge amount of works from the last decade highlighted that elastin plays also a pivotal role in various pathophysiological processes through the release of elastin-derived peptides (EDP), including vascular and metabolic diseases." (PMID 34903296, 2021).
neurodegenerative disease (4 papers, 2022 to 2025). A disorder of the central nervous system characterized by gradual and progressive loss of neural tissue and neurologic function. "Unfortunately, the role of elastin and the extracellular matrix in the development of neurodegenerative diseases and aging of the nervous system is very poorly studied." (PMID 34374904, 2022). "Studies on the mechanism of action of EDPs as sequestered antigens inducing the production of anti-elastin antibodies may explain the basis of neurodegenerative diseases as autoimmune reactions." (PMID 34374904, 2022).
respiratory diseases (4 papers, 2012 to 2024). "Especially MMP-9 and MMP-12 have been associated with elastin degradation and hence with cardiovascular and respiratory diseases." (PMID 22818364, 2012). "Remodeling of ECM, especially elastin and collagen, has been involved in the pathophysiology of several respiratory diseases including COPD which is a serious global health problem with increasing morbidity, mortality, and economic burden." (PMID 39830508, 2024). "The technique and biomarkers used in the present study allowed for investigation of elastin degradation predominantly produced by specific proteinases, known to be up-regulated in respiratory diseases and therefore more carefully quantify the aspects of the elastin degradome." (PMID 30858579, 2019). "Our hypothesis was that elastin degradation by MMP-9 and -12, may provide information to aid diagnosis and progression of respiratory diseases." (PMID 22818364, 2012). "Although elastin fragments generated by aggrecanases and cathepsins were identified and may serve as biomarker targets for other indications, our study focused on the activity of MMP-9 and -12 because these proteases are expressed in respiratory diseases." (PMID 22818364, 2012).
adenocarcinoma (3 papers, 2015 to 2025). A common cancer characterized by the presence of malignant glandular cells. "CD26-expressing adenocarcinomas showed a higher expression of Vimentin and Elastin (p = 0.0027 and p < 0.0001, respectively), while E-cadherin expression was lower in this group of patients (p = 0.0021)." (PMID 41426321, 2025). "The levels of Vimentin and Elastin were significantly higher in CD26-positive tumors compared to CD26-negative adenocarcinoma tissues (p = 0.0027 and p < 0.0001, respectively)." (PMID 41426321, 2025). "Furthermore, CD26-expressing adenocarcinomas showed a higher expression of the EMT phase markers Vimentin and Elastin." (PMID 41426321, 2025).
heart disease (3 papers, 2021 to 2025). "Although AE, RT, and CT have been shown to improve various cardiovascular metrics, age-related changes in blood vessels, such as elastin fiber degeneration and increased collagen, may obscure the immediate benefits on DBP for high-risk groups like the elderly, obese, or those with heart disease." (PMID 40083821, 2025).
vasculopathy (3 papers, 2022 to 2025). "We showed that PAH vasculopathy is characterized by high steady-state levels of Cat S and degradation of elastin lamina in the SMCs lining the proximal and distal PAs in both patients with PH and a rodent model." (PMID 36293172, 2022).
bacterial infection (2 papers, 2013 to 2023). "Activation of airway neutrophils during bacterial infection results in the release of various mediators such as NE that degrades proteins (e.g., elastin, fibronectin), leading to disease progression." (PMID 24209388, 2013).
skin disorder (2 papers, 2021 to 2023). Any deviation from the normal structure or function of the skin or subcutaneous tissue that is manifested by a characteristic set of symptoms and signs. "Therefore, transdermal administration of sialidase is expected to be useful for improvement of wrinkles and skin disorders due to loss of elastin." (PMID 33558588, 2021). "It was hypothesized that CPL may be a generalized skin disorder, affecting not only the dermis of the distal extremities but also the elastin-rich skin of the neck." (PMID 37235431, 2023). "No changes were observed in the elastin network of other organs, including the elastin-rich aorta, leading to the hypothesis that CPL is a generalized skin disorder." (PMID 37235431, 2023).
communicable disease (1 paper, 2025). "The resulting airspace enlargement correlates with an increase in elastin crosslink density, and the graph of that relationship corresponds to that associated with the transmission of a communicable disease." (PMID 40141701, 2025).
neurodevelopmental disorder (1 paper, 2022). A behavioral and cognitive disorder with onset during the developmental period that involves impaired or aberrant development of intellectual, motor, or social functions. "CNVs in chromosome 7q11.23 encompassing the ELN gene are associated with syndromic neurodevelopmental disorders." (PMID 36153334, 2022).
ELN also shares sentences with these, for which no sentence is quoted: end-stage renal disease (6 papers); kidney diseases (4); metabolic syndrome (3); osteoporosis (3); acne inversa (2); aortic valve disease (2); arteriolosclerosis (2); colon (2); Cornelia de Lange syndrome (2); erectile dysfunction (2); Erythema (2); Hypercalcemia (2); hypertrophy (2); hypoplastic left heart syndrome (2); ichthyosis (2); lung adenocarcinoma (2); mucopolysaccharidoses (2); myocardial ischemia (2); non-alcoholic fatty liver disease (2); nonalcoholic steatohepatitis (2); primary open-angle glaucoma (2); pulmonary stenosis (2); Renal failure (2); respiratory failure (2); subarachnoid hemorrhage (2); Turner syndrome (2); Vascular Ehlers Danlos syndrome (2); vasculitis (2); acrodermatitis enteropathica (1); acute myocardial infarction (1).
A further 111 diseases each share a sentence with ELN in 1 paper.